MSH6 (mutS homolog 6)
Diseases named in the same sentence as MSH6 in open-access papers (continued):
Sharing a sentence is not in itself a finding about the gene and the disease.
rectal cancer (20 papers, 2006 to 2025). A primary or metastatic malignant neoplasm that affects the rectum. "In addition, xeroderma pigmentosum group G (XPG) C46T rs1047768 and mutS homolog 6 (MSH6) rs3136228 have been significantly associated with response to nCRT in rectal cancer." (PMID 28272347, 2017). "Other authors reported in MSH6 G39E homozygous patients an increased risk of rectal cancer only." (PMID 24383517, 2014). "One novel missense mutation in the MSH6 gene (c.3955A>C, p.Lys1319Gln) was identified in patient 14B-ON3654BD1 (female, rectal cancer at the age of 34 years)." (PMID 28445943, 2017). "However, the pre-treated rectal carcinoma in a patient with MSH6-related LS of the French collective was MSI‐H." (PMID 37874379, 2023). "We could not identify any rectal cancer with a concurrent MLH1/PMS2 and MSH6 loss." (PMID 36387226, 2022).
endometrial tumors (17 papers, 2007 to 2025). "Hampel and colleagues found all 6 endometrial tumours from path_MSH6 carriers were MMR deficient, but just 3/6 were MSI-H; despite this, tumours were triaged for MMR germline sequencing using the results of MSI analysis, and only a subset underwent MMR-IHC." (PMID 32941469, 2020). "Her endometrial tumor harbored a somatic MSH6 mutation without a detectable germline mutation in any of the mismatch repair genes; however, she was found to have a pathogenic germline CDH1 mutation (c.715G > A (p.Gly239Arg) on NGS." (PMID 40242369, 2025). "However, IHC was doubtful for MSH6 in one of the endometrial tumors and the authors concluded pMMR as the molecular techniques showed concordance." (PMID 34145315, 2021). "At the same time, immunohistochemical study of the endometrial tumor unambiguously established the absence of expression of the MSH6 protein." (PMID 33937060, 2021).
hereditary cancer syndromes (17 papers, 2016 to 2024).
hereditary cancer (16 papers, 2010 to 2024). Malignant neoplasms occurring in families at a rate greater than that expected by chance and caused by germline mutations in a specific gene. "Missense R1076C mutation of MSH6 gene is located on the ATPase domain and has been evaluated as likely pathogenic in ClinVar database (Variation ID: 89357) with multiple evidence associating this mutation with HNPCC and hereditary cancer-predisposing syndrome." (PMID 33422121, 2021).
Fanconi anemia (15 papers, 2016 to 2025). Fanconi anemia (FA) is a hereditary DNA repair disorder characterized by progressive pancytopenia with bone marrow failure, variable congenital malformations and predisposition to develop hematological or solid tumors. "Most detected variants affected the Fanconi anemia/DNA repair pathway (34%, ATM, FANCA, FANCI, MLH1, MSH6, POLE, RAD51C, RAD51D) followed by mutations altering the SWI/SNF (SWItch/sucrose non-fermentable) complex (22%, ARID1A and SMARCA4)." (PMID 34200508, 2021). "Specifically, we identified as interactors, or in our phosphoproteome analysis, repair proteins such as MSH6 (DNA mismatch repair protein Msh6) and FANCA (Fanconi Anemia, complementation group A)." (PMID 28710492, 2017).
sarcoma (15 papers, 2017 to 2024). A usually aggressive malignant neoplasm of the soft tissue or bone. "Age at sarcoma diagnosis was ≥45 years in all patients except the MSH6 mutation carrier, whose age-at-diagnosis was 24 years old." (PMID 28878254, 2017). "In a study of sarcomas, seven proteins related to overall survival (AMPKALPHA, CHK1, S6, ARID1A, RBM15, ACETYLATUBULINLYS40, and MSH6) were discovered using the proteomics data of different sarcoma subtypes." (PMID 35875106, 2022). "MSH6-altered sarcomas had a higher mutation count than sarcomas without MSH6 alteration (median 14.0 x 3.0, p<0.01)." (PMID 36741731, 2022). "Both germline and somatic hits were found in the ATM, CDC73, MLH1, MSH6, POLG, and KCNQ1 genes, which have no previously known connection with sarcoma." (PMID 39594770, 2024).
brain tumors (14 papers, 2016 to 2025). "Herein, in the two new cases of CMMRD by biallelic MSH6 mutations with brain neoplasm, the IHC study of MMR proteins was crucial to arrive at the correct molecular diagnosis." (PMID 33924881, 2021). "We demonstrate this by the case of two children with biallelic MSH6 germline mutations and brain tumors, and a review of the literature." (PMID 33924881, 2021). "In contrast, dinucleotide repeat markers have been shown to be most useful in CMMRD-associated brain tumors, although they are insensitive to MSH6 deficiency." (PMID 33924881, 2021). "Carriers of biallelic MSH6/PMS2 mutations have higher rates of brain tumors and Lynch syndrome associated tumors." (PMID 32168907, 2020). "Pediatric CMMRD patients presenting with brain tumors commonly have biallelic loss of PSM2 or MSH6, ultra-hypermutated pediatric GBM, and a unique MMR first/POLE second mutational signature." (PMID 31604779, 2019). "In addition, patients with biallelic mutations in MSH6 have a significantly higher incidence of brain tumors manifested mainly in the first 10 years of life when compared to other mutations." (PMID 39093498, 2024). "The aim of this report is to draw attention to the peculiar IHC profile that characterizes CMMRD syndrome and to review the difficulties in reaching an accurate diagnosis by describing the case of two siblings with biallelic MSH6 germline mutations and brain tumors." (PMID 33924881, 2021). "Consistently, bi-allelic germline MSH6 R1076C mutation of our patient led to the development of CRC in the third decade of life but without any hematological malignancy or brain tumor." (PMID 33422121, 2021). "In addition, those brain tumors retaining PMS2 or MSH6 expression were also identified applying the clinical scoring system." (PMID 33924881, 2021). "Nevertheless, Cahill and colleagues detected MSH6 mutations in 3 of 14 recurrent brain tumors, but no mutation of MSH6 in 40 pretreatment GBM, suggesting that loss of MSH6 expression might set in during temozolomide treatment." (PMID 32937743, 2020). "It showed retained expression of all proteins, except MSH6, in both primary brain tumors and nontumor cells, such as endothelium (white arrow)." (PMID 40880425, 2025). "The post‐treatment recurrent brain tumors exhibited a decrease in expression of the mismatch repair (MMR) proteins, MSH6 and MLH1, but their methylated MGMT status did not changed." (PMID 26778701, 2016).
osteosarcoma (14 papers, 2017 to 2025). A usually aggressive malignant bone-forming mesenchymal neoplasm, predominantly affecting adolescents and young adults. "Based on these findings, CSE1L is correlated with MSH6 in tumor samples and is associated with poor prognosis in patients with osteosarcoma." (PMID 28387323, 2017). "More importantly, this study is the first to provide experimental evidence for the significance of the interaction between CSE1L and MSH6 in osteosarcoma cells, and reveals the molecular mechanism that may underlie CSE1L-mediated tumorigenesis." (PMID 28387323, 2017). "Notably, CSE1L expression was correlated with MSH6 expression in tumor samples and was associated with poor prognosis in patients with osteosarcoma." (PMID 28387323, 2017). "Therefore, CSE1L associates with MSH6 in osteosarcoma cells." (PMID 28387323, 2017). "CRISPR-Cas9-mediated knockout of MSH6, MSH3, and MLH1 in U2OS osteosarcoma cells resulted in the complete loss of each protein (Figure S2A22)." (PMID 38749429, 2024). "In osteosarcoma cells, CSE1L, a positive regulator of MSH6 protein, is associated with poor patient prognosis." (PMID 39430746, 2024). "Our research team has been committed to the study of this MSH6 protein with different functions and reported the functional connection between MSH6 and the tumorigenesis and development of osteosarcoma." (PMID 34941572, 2021). "By co-immunoprecipitation and RNA-seq analysis, CSE1L was found to interact with mutS homolog 6 (MSH6) and function as a positive regulator of MSH6 protein in osteosarcoma cells." (PMID 28387323, 2017). "We found that there was a significant correlation between expression of both CSE1L and MSH6 in osteosarcoma tissues (R = 0.697, P < 0.001)." (PMID 28387323, 2017). "Further validation showed that increased CSE1L expression in osteosarcoma was associated with poor prognosis and that there was a positive correlation between CSE1L and MSH6 in osteosarcoma." (PMID 28387323, 2017). "To determine the role of MSH6 in osteosarcoma in vivo, we generated a stable MSH6-knockdown MNNG/HOS cell line." (PMID 28387323, 2017). "To investigate the underlying mechanism, we used co-immunoprecipitation and RNA-seq techniques and found that CSE1L interacted with and functioned through MSH6 in osteosarcoma cells." (PMID 28387323, 2017). "A rescue study showed that decreased growth of osteosarcoma cells by CSE1L knockdown was reversed by MSH6 overexpression, indicating that the activity of CSE1L was an MSH6-dependent function." (PMID 28387323, 2017). "We found that MSH6 was highly expressed in osteosarcoma cells." (PMID 28387323, 2017). "Then, we detected the expression of MSH6 in osteosarcoma cells and osteoblastic cells." (PMID 28387323, 2017). "Consequently, these results support the conclusion that CSE1L interacts with MSH6 and functions as a positive regulator of MSH6 protein in osteosarcoma cells." (PMID 28387323, 2017). "We found that knockdown of MSH6 significantly inhibited the growth of osteosarcoma cells." (PMID 28387323, 2017). "In addition to presenting evidence supporting an interaction between CSE1L and MSH6, we found that CSE1L and MSH6 were co-localized in cells from two different osteosarcoma cell lines." (PMID 28387323, 2017). "This is the first study to demonstrate an interaction between CSE1L and MSH6 in osteosarcoma cells." (PMID 28387323, 2017). "Next, MSH6-specific siRNA was used to knockdown MSH6 in osteosarcoma cells." (PMID 28387323, 2017). "In addition, MSH6 knockdown inhibited osteosarcoma cell proliferation in vitro and in vivo." (PMID 28387323, 2017). "Therefore, intervention via the CSE1L/MSH6 axis may be a feasible and effective strategy in the treatment of osteosarcoma." (PMID 28387323, 2017).
osteosarcoma (continued). "In addition, a positive correlation between CSE1L and MSH6 was found in osteosarcoma." (PMID 28387323, 2017). "Since CSE1L interacts with MSH6 and affects its protein expression and stability in osteosarcoma cells, it is plausible that CSE1L functions through MSH6 and that MSH6 has an important role in osteosarcoma cell proliferation." (PMID 28387323, 2017). "However, the role of MSH6 in osteosarcoma is unknown, and whether CSE1L functions through MSH6 is largely unknown." (PMID 28387323, 2017).
bladder cancer (13 papers, 2019 to 2026).